ICAM1 (intercellular adhesion molecule 1)
Diseases named in the same sentence as ICAM1 in open-access papers (continued):
Sharing a sentence is not in itself a finding about the gene and the disease.
Hypercholesterolemia (24 papers, 2006 to 2026). An increased concentration of cholesterol in the blood. "Soluble CSF VCAM1 and ICAM1 levels, which reflect changes in the endothelial layer of the BBB, have been correlated with CNS inflammatory changes, while in the periphery, VCAM1, and ICAM1 are upregulated in hypercholesterolemia and associated with early atherogenic lesions." (PMID 36927447, 2023). "ICAM-1 levels were significantly reduced in both groups after the consumption of black garlic (p < 0.001), being 10.6% in the group with hypercholesterolemia and 15.7% in the healthy group." (PMID 37513556, 2023). "Naringin inhibits hypercholesterolemia-induced intercellular adhesion molecule-1 (ICAM-1) expression on endothelial cells." (PMID 29492183, 2018). "Additionally, naringin inhibited the hypercholesterolemia-induced expression of intercellular adhesion molecule 1 (ICAM1) on endothelial cells, suggesting that the suppression of ICAM1 contributes to its anti-atherogenic effect." (PMID 39309005, 2024). "Decreased levels observed of endothelial adhesion molecules, VCAM-1 and ICAM-1, may indicate a better prognosis for complications of hypercholesterolemia." (PMID 37513556, 2023). "In addition, naringin has been shown to lower hypercholesterolemia-induced intercellular adhesion molecule-1 (ICAM-1) expression on endothelial cells of hypercholesterolemic rabbits." (PMID 32962323, 2017). "Indeed, 90-day administration of atorvastatin combined with ezetimibe (40 + 10 mg/day) was associated with a significant reduction in serum levels of ICAM-1 and hsCRP in patients with hypercholesterolemia, but no such effect was observed for ezetimibe monotherapy (10 mg/day)." (PMID 34492054, 2021). "Interestingly, the fungal metabolite lovastatin, which belongs to the statin compounds used in the treatment of hypercholesterolemia, was shown to bind LFA-1 and inhibit the interaction with ICAM-1." (PMID 17078873, 2006).
preeclampsia (24 papers, 2010 to 2025). Preeclampsia is a hypertensive disorder of pregnancy that is characterized by new-onset hypertension with proteinuria presenting after 20 weeks of gestation, and depending on mild or severe forms may initially present with severe headache, visual disturbances, and hyperreflexia. "In the present study, we aimed to examine the association between K469E polymorphism at exon 6 of the ICAM-1 gene and preeclampsia in south east of Iran." (PMID 24591755, 2014). "The current view on preeclampsia suggests that preeclampsia has an exaggerated maternal systemic immune response component, and indeed, blood-group antigens influence the bioavailability of E-selectin, TNF-alpha and ICAM1, factors implicated in the pathogenesis of preeclampsia." (PMID 21799738, 2011). "Since cell invasion requires proteolysis of the extracellular matrix, dysregulation of the cell adhesion molecules ICAM-1, VCAM-1, and E-selectin are implicated in preeclampsia development." (PMID 39409189, 2024). "This study investigates the associations of ICAM-1, VCAM-1, and E-selectin gene variants (rs3093030, rs3783605, and rs1805193, respectively) with preeclampsia comorbid with HIV infection in women of African ancestry." (PMID 39409189, 2024). "Single-nucleotide polymorphisms of ICAM-1, VCAM-1, and E-selectin will have downstream effects on their release into circulation, thus affecting placentation in preeclampsia." (PMID 39409189, 2024). "Increases in in adiponectin levels in preeclampsia have anti-inflammatory, and vascular protective activities and lead to decreased expression of cell adhesion molecules (E-selectin, ICAM-1, VCAM-1), and suppression of vascular inflammation." (PMID 37964253, 2023). "Women with a history of preeclampsia had higher body mass index (p = 0.006), blood pressure (p<0.001) and plasma levels of interleukin-6 (p = 0.005) and soluble intercellular adhesion molecule-1 (sICAM-1) (p = 0.014)." (PMID 29894501, 2018). "Real-time PCR analysis showed increased expression of inflammatory markers TNF-α, TLR-9 and ICAM-1 respectively in endothelial cells treated with preeclampsia plasma." (PMID 27604418, 2016). "Intercellular adhesion molecule-1 (ICAM-1), vascular adhesion molecule-1 (VCAM-1), and E-selectin are cell adhesion molecules that play a significant role in inflammation and are implicated in the pathophysiology of preeclampsia development and HIV infection." (PMID 39409189, 2024). "In addition, in serum and placenta from preeclampsia patients, increased ICAM-1 expression was found." (PMID 32751152, 2020). "Furthermore we showed a significant increase in ICAM-1 gene expression (marker of vascular dysfunction) in HUVEC treated with preeclampsia plasma." (PMID 27604418, 2016). "Forty women with preeclampsia and matched controls were analyzed for ICAM-1, VCAM-1 and E-selectin." (PMID 22952728, 2012). "It is widely accepted that ICAM-1, VCAM-1, and E-Selectin are dysregulated, thereby affecting trophoblast invasion and angiogenesis, the hallmarks of preeclampsia development." (PMID 39409189, 2024). "More specifically, the immune expression of ICAM-1, VCAM-1, and E-selectin within cyto- and syncytiotrophoblast cells are dysregulated in preeclampsia, indicating their role in defective placentation." (PMID 39409189, 2024). "Additionally, the C allele of the ICAM-1 (rs3093030 C>T) and G allele of the VCAM-1 (rs3783605 A>G) genes were found to have a greater role in the co-morbidity and may be considered as a risk factor for preeclampsia development in women of African ancestry." (PMID 39409189, 2024). "In early-onset preeclampsia, biomarkers such as FLT-1, ICAM (intercellular adhesion molecule 1), and NAD(P)H (nicotinamide adenine dinucleotide phosphate) oxidase are increased compared in late-onset preeclampsia." (PMID 30363976, 2018).
preeclampsia (continued). "S1P also induces the activation of inflammatory mediators, such as VCAM-1, ICAM-1 and COX, which are elevated in both blood and placenta during preeclampsia." (PMID 28542236, 2017). "Circulating levels of the pro-inflammatory cytokines IL-6 and TNF-α, the chemokines IL-8, IP-10 and MCP-1, as well as the adhesion molecules ICAM-1 and VCAM-1, were raised in preeclampsia compared with healthy pregnancy, resulting in an overall pro-inflammatory systemic environment." (PMID 21126355, 2010). "However, it seems that higher levels of endothelial activators such as VCAM and intercellular adhesion molecule-1 (ICAM), more significant changes of placenta-derived growth factor (PlGF), and more developed inflammatory states occur in preeclampsia than in IUGR." (PMID 36675415, 2023).
triple-negative breast carcinoma (24 papers, 2015 to 2025). An invasive breast carcinoma which is negative for expression of estrogen receptor (ER), progesterone receptor (PR), and human epidermal growth factor receptor 2 (HER2). "Intracellular adhesion molecule 1 (ICAM1) has been implicated in a variety of immune and inflammatory responses, in addition to associate with triple negative breast cancer (TNBC)." (PMID 30082828, 2018). "Distribution of Met and its co-receptors in the human mammary gland remains poorly defined; however, strong expression of Met, ICAM-1, and CD44v6 has been associated with triple-negative breast cancers and correlated with poor prognosis." (PMID 26165517, 2015). "Low ICAM-1 has been correlated with poor prognosis in triple-negative breast cancer, where low-ICAM1 was found to promote macrophage M2 polarization along with T-cell exhaustion." (PMID 39596815, 2024). "Immunohistochemical results showed that: the expression of ICAM-1 was 4.767 ± 1.278 in triple-negative breast cancer tissues, 2.700 ± 2.548 in paracancerous tissues, and 3.800 ± 1.105 in positive lymph nodes." (PMID 38799250, 2024). "This study introduces a novel lipid nanoparticle (LNP) small interfering RNA (siRNA) delivery system targeting intercellular adhesion molecule-1 (ICAM-1) for triple-negative breast cancer (TNBC)." (PMID 40125243, 2024). "In this study, we found that intercellular adhesion molecule-1 (ICAM-1) on triple-negative breast cancer (TNBC) cells and CD11b on neutrophils mediate tumor cell–neutrophil binding." (PMID 37345070, 2023). "Several ICAM-1-directed therapeutics have been developed for potential application in solid tumors with poor survival outcomes, such as triple-negative breast cancer." (PMID 37237555, 2023). "Recently, ICAM1 has been shown as a promoter of triple-negative breast cancer (TNBC) metastasis through mediating homotypic CTC-cluster formation and transendothelial migration." (PMID 36949770, 2023). "This is in agreement with the results obtained with MDA-mb-231 triple-negative breast cancer cells exposed to parabolic flight manoeuvres, which exhibited an early upregulation of ICAM1." (PMID 34445479, 2021). "Chained strand displacement events are triggered after the capture probes detect the surface biomarkers epidermal growth factor receptor (EGFR) and intercellular adhesion molecule-1 (ICAM-1) in the triple-negative breast cancer cell MDA-MB-231." (PMID 34745974, 2021). "TNBC (triple-negative breast cancer) cells exposed to short-term microgravity obtained by parabolic flight maneuvers kept all signs of a more aggressive phenotype, as elevations of ICAM1 and Vascular cell adhesion protein 1 (VCAM1) proteins occurred quickly." (PMID 32013031, 2020). "In triple negative breast cancer, ICAM-1 has been shown to promote EMT through different pathways." (PMID 40566630, 2025). "Interestingly, ICAM1 was found to activate EMT via TGF-beta signalling in triple-negative breast cancers." (PMID 41465326, 2025). "The involvement of ICAM-1 in triple negative breast cancer is the primary topic of this article." (PMID 38799250, 2024). "Similarly, intercellular adhesion molecule-1 (ICAM-1) antibody-conjugated IONPs were synthesized to target the overexpression of ICAM-1 in human triple-negative breast cancer cell lines and were utilized as magnetic resonance imaging (MRI) probes." (PMID 39768040, 2024). "ICAM1 is also considered a target in triple-negative breast cancer." (PMID 28977919, 2017). "Moreover, ICAM-1 has recently been identified as a molecular target for triple-negative breast cancers." (PMID 26165517, 2015). "In triple-negative breast cancer cells, ablation of ICAM-1 expression suppresses while overexpression of ICAM-1 increases dimerization and phosphorylation of EGFR and activation of the EGFR-dependent signaling." (PMID 39594667, 2024).
triple-negative breast carcinoma (continued). "In triple negative breast cancer (TNBC), the ICAM1 antibody significantly reduced cell migration and ICAM1 could act as a molecular target for TNBC." (PMID 36803413, 2023).
osteosarcoma (22 papers, 2013 to 2025). A usually aggressive malignant bone-forming mesenchymal neoplasm, predominantly affecting adolescents and young adults. "Interleukin‐6 (IL‐6) activated the expression of ICAM‐1 and contributed to the migration of human osteosarcoma cells through integrin‐linked kinase (ILK)/Akt/AP‐1 pathways." (PMID 36772869, 2023). "The screening of candidate targets in NGF-treated osteosarcomas revealed that the NGF-induced upregulation of VCAM-1 was more pronounced than that of ICAM-1 or CCL2." (PMID 39247831, 2024). "Osteosarcoma cells colonize the lungs more quickly by upregulating ICAM1 expression in response to tumor‐derived IL‐6, which facilitates glycolytic metabolism in tumor cells by activating the MEK/ERK/HIF‐1α pathway." (PMID 36772869, 2023). "CX3CL1 induced cell migration in human osteosarcoma cells via upregulating ICAM-1 expression mediated by CX3CR1/PI3K/Akt/NF-κBpathway44." (PMID 37770496, 2023). "For example, an overexpressed intercellular adhesion molecule-1 (ICAM-1) can promote osteosarcoma metastasis." (PMID 37893141, 2023). "TGF-α/EGFR interacted PI3K/Akt activation, then activated NF-κB, increased the expression of ICAM-1, and contributed to the migration of human osteosarcoma cells." (PMID 33436536, 2021). "IL6 also increased the expression of intercellular adhesion molecule-1 (ICAM-1) and promoted migration in human osteosarcoma cells." (PMID 33436536, 2021). "It has been shown that TGFα in osteosarcoma increases ICAM-1 expression levels, transforming cancer cells into a more motile, invasive and adhesive phenotype." (PMID 30657059, 2019). "The fractalkine/CX3CR1 axis activated ICAM-1 expression in osteosarcoma and promoted the migration of osteosarcoma cells." (PMID 28903329, 2017). "Another study on osteosarcoma revealed that ICAM-1 is upregulated by interleukin-6 and is responsible for the migration of osteosarcoma cells." (PMID 28903329, 2017). "In conclusion, our results indicate that fractalkine promotes cell migration and metastasis of osteosarcoma by upregulating ICAM-1 expression." (PMID 28903329, 2017). "Fractalkine induced cell migration by upregulating intercellular adhesion molecule-1 (ICAM-1) expression via CX3CR1/PI3K/Akt/NF-κB pathway in human osteosarcoma cells." (PMID 28903329, 2017). "In our present study, we confirmed that the PI3K/Akt signal cascade is involved in fractalkine/CX3CR1-induced ICAM-1 expression and lung metastasis in osteosarcoma." (PMID 28903329, 2017). "Our results also demonstrated that CX3CR1/PI3K/Akt/NF-κB mediates ICAM-1 expression, subsequently regulating cell migration and lung metastasis in osteosarcoma." (PMID 28903329, 2017). "The same suppressive effect was observed in the dominant-negative mutant of PI3K p85-transfected cells, indicating that PI3K works downstream of AREG to affect the migration of osteosarcoma and to regulate the expression of ICAM-1." (PMID 26503469, 2015). "In summary, our findings suggested that AREG promoted cancer cell motility of osteosarcoma and up-regulated the expression of ICAM-1 through the EGFR/PI3K/Akt/NF-κB signaling pathway." (PMID 26503469, 2015). "Overall these results imply that AREG and EGFR act through the PI3K/Akt-dependent signaling pathway to enhance ICAM-1 expression and cell migration in human osteosarcoma cells." (PMID 26503469, 2015). "To understand the level of AREG between the normal and the malignant cells, we examined the levels of AREG and ICAM-1 between hFOB 1.19 and osteosarcoma (MG63 and U2OS)." (PMID 26503469, 2015). "Using cellular-level experiments, we also demonstrate that AREG promotes ICAM-1 expression and migration in osteosarcoma." (PMID 26503469, 2015). "Accordingly, MSCs may interact with osteosarcoma CSCs to increase the levels of adhesion molecules, such as the intercellular adhesion molecule 1 (ICAM-1), that are responsible for tumor extravasation." (PMID 34198693, 2021).
osteosarcoma (continued). "ICAM-1 is important in the metastatic spread of osteosarcoma cancer cells." (PMID 30657059, 2019). "Furthermore, fractalkine expression was positively correlated with ICAM-1 expression in osteosarcoma specimens." (PMID 28903329, 2017). "Finally, we showed a clinical correlation between CX3CL1 expression and ICAM-1 expression as well as tumor stage in human osteosarcoma tissues." (PMID 28903329, 2017). "Our previous study showed the key role of ICAM-1 in osteosarcoma metastasis." (PMID 28903329, 2017). "Furthermore, osteosarcoma cells transfected with IKKα and IKKβ dominant mutants showed inhibited fractalkine-induced cell migration and ICAM-1 expression." (PMID 28903329, 2017). "Moreover, IHC results show fractalkine expression is positively correlated with ICAM-1 expression and tumor stage in osteosarcoma." (PMID 28903329, 2017). "In this study, the role of ICAM-1 in osteosarcoma metastasis was confirmed." (PMID 28903329, 2017). "According to the results described thus far, we can hypothesize that elevated levels of AREG in osteosarcoma stimulate cancer cell migration by promoting ICAM-1 expression." (PMID 26503469, 2015). "In our previous study, we determined that elevated ICAM-1 expression was promoted the metastasis of osteosarcoma: the expression level of ICAM-1 was elevated in two metastatic osteosarcoma cell lines and ICAM-1 siRNA reduced their tumor cell migration (transforming growth factor alpha)." (PMID 26503469, 2015). "We also found that the expression of ICAM-1 was elevated in osteosarcoma cells." (PMID 26503469, 2015). "On the other hand, interleukin (IL)-6 enhanced osteosarcoma migration involves ICAM-1 expression." (PMID 23803661, 2013). "AREG upregulates ICAM-1 expression via EGFR/PI3K/Akt/NF-κB signaling and promotes the cancer cell viability of osteosarcoma." (PMID 36843929, 2023). "Transfecting osteosarcoma cells with PI3K and Akt dominant mutants (DN-PI3K and DN-Akt) also inhibited fractalkine-induced cell migration and ICAM-1 expression." (PMID 28903329, 2017). "According to these results, fractalkine induced ICAM-1 expression and cell migration through the PI3K/Akt signaling pathway in osteosarcoma." (PMID 28903329, 2017). "Our findings revealed a relationship between osteosarcoma metastatic potential and AREG expression and the modulating effect of AREG on ICAM-1 expression." (PMID 26503469, 2015). "We determined that two osteosarcoma cell lines expressed high levels of AREG and that further AREG stimulation enhanced ICAM-1 expression, thus contributing to the increased cell migration of osteosarcoma." (PMID 26503469, 2015). "Conversely, also osteosarcoma-derived extracellular vesicles exert epigenetic alterations in surrounding MSCs and expression of genes related to bone microenvironment remodeling, namely MMP1, VEGF-A, and ICAM1." (PMID 37176108, 2023). "Among them, the key hub genes were ICAM1 (intercellular adhesion molecule 1), HRAS (Ras family small GTP binding protein H‐Ras), PTGS2 (prostaglandin‐endoperoxide synthase 2, also known as COX‐2), and FOS (FBJ osteosarcoma oncogene)." (PMID 36772869, 2023). "Additionally, DHTS has been shown to impair the migration of osteosarcoma cells (143B) by downregulating cell adhesion markers like VCAM-1 and ICAM-1." (PMID 34319041, 2021). "To identify the potential downstream target genes related to lincFOXF1 in osteosarcoma, we conducted qRT‐PCR to assess expression of multiple molecules (such as N‐cadherin, Integrin, CD44, ICAM‐1, Vimentin, Fibronectin, GIT1 and FOXF1) in osteosarcoma cells after gain or loss of lincFOXF1 function." (PMID 32945076, 2020). "Therefore, we measured the expression levels of ICAM-1 mRNA and protein in AREG treated osteosarcoma cells and determined that these levels were increased by AREG treatment in a dose-dependent and time-dependent pattern." (PMID 26503469, 2015).